BPY2 (basic charge Y-linked 2)
Synonyms: BPY2A; VCY2; VCY2A
Tractability: No criterion of Open Targets' tractability assessment is met for any kind of drug.
Gene: Protein-coding gene on chromosome Y (22,973,819 to 23,005,465, forward strand). Ensembl gene ENSG00000183753.
Gene Ontology:
Molecular function: HECT domain binding; protein binding
Biological process: spermatogenesis; single fertilization
Cellular component: nucleus
Homologues: Paralogues in human: BPY2B (100% identical), BPY2C (100% identical).
Diseases named in the same sentence as BPY2 in open-access papers:
BPY2 is named in the same sentence as 5 diseases in open-access papers, as found by Europe PMC text mining. Sharing a sentence is not in itself a finding about the gene and the disease. The quoted sentences say what the papers report.
Azoospermia (5 papers, 2016 to 2024). Absence of any measurable level of sperm,whereby spermatozoa cannot be observed even after centrifugation of the semen pellet. "Finally, inside the AZFc region, the candidate genes for infertility are Chromodomain Y, Y-linked (CDY), Basic charge, Y-linked, 1 (BPY1), Basic protein Y2, Y-linked (BPY2) and Deleted in Azoospermia (DAZ)." (PMID 31905733, 2019). "CNVs of DAZ, CDY1, and BPY2 are correlated with decreased total motile sperm count and lead to azoospermia and moderate/severe oligozoospermia phenotypes." (PMID 34983649, 2022). "Recent studies on the genetics of azoospermia have identified specific genes associated with a large spectrum of testis phenotypes, from hypospermatogenesis (USP9Y) to residual spermatogenesis (PRY, RBBMY, BPY2, DAZ)." (PMID 38403804, 2024). "DAZ, CDY1, BPY2, and PRY are some genes located in AZFc which can be directly related to the incidence of oligozoospermia and azoospermia." (PMID 34983649, 2022).
Infertility (2 papers, 2021 to 2023). "Three patients and three reference men carried a secondary b2/b4 duplication adding one or more amplicons of [two DAZ – two BPY2 – one CDY1] genes with no apparent effect on infertility status (Fisher’s exact test, p=0.34)." (PMID 33781384, 2021). "Previously, no study had undertaken re-sequencing of the retained DAZ, BPY2, and CDY genes along with the assessment of the Y haplogroup, dosage, and retained/deleted genes in the gr/gr or b2/b3-deleted chromosomes in both infertile men and controls." (PMID 33781384, 2021).
male infertility (1 paper, 2019). The inability of the male to effect fertilization of an ovum after a specified period of unprotected intercourse. "BPY2 possible role in male infertility upon duplication has been suggested as well." (PMID 31905733, 2019).
tumor (1 paper, 2022). "Furthermore, data mining of RNA-Seq data of 27 male tumor/non-tumor paired samples from The Cancer Genome Atlas (TCGA) showed that DAZ1 and BPY2 are frequently down-regulated in HCC patients." (PMID 34983649, 2022).
BPY2 also shares sentences with these, for which no sentence is quoted: prostate tumor (1 paper).